GLI1 (GLI family zinc finger 1)
Diseases named in the same sentence as GLI1 in open-access papers (continued):
Sharing a sentence is not in itself a finding about the gene and the disease.
Ewing sarcoma (continued). "Altogether, these results identify Gli1 as a promising therapeutic target in Ewing sarcoma and demonstrate that GANT61, through inhibition of Gli1 transcriptional activity, may be a promising therapeutic strategy hindering ES tumor progression, specifically primary tumor growth." (PMID 33228057, 2020). "Next, expression levels of eight EWS-FLI1 associated target genes (GLI1, NEX2.2, CyclinD, c-MYC, NR01B, IGF1R, EZH2, and CD99) which were known to be upregulated, and three genes (FOXO1, IGFBP3, and LOX) known to be down regulated in Ewing’s sarcoma was assessed." (PMID 28775288, 2017). "However, since Ewing sarcoma is mainly a pediatric cancer, it is necessary to further investigate its effects and to be prudent when designing clinical studies given the roles of the Shh–GLI1 pathway in development." (PMID 26258070, 2015). "Both survival and tumorigenesis of the Ewing sarcoma family of tumors are keyed to the function of EWS-FLI1, and it was shown that Gli1 is a transcriptional target of EWS-FLI1." (PMID 37815662, 2023). "In TC32 Ewing sarcoma cells, the knockdown of EWS/FLI1 using RNA interference resulted in a reduction in GLI1 expression levels." (PMID 37894854, 2023). "Cellular screening identified the first such inhibitors, GANT-61/GANT-58 which block GLI transcription by interfering GLI1- DNA binding and effectively suppress the growth of tumors with elevated GLI1 expression, such as Ewing’s sarcoma." (PMID 37213270, 2023). "In TC32 Ewing sarcoma cells, the silencing of EWS/FLI1 through RNA interference led to a corresponding decrease in GLI1 expression levels." (PMID 37894854, 2023). "Recently, the upregulation of the Zinc finger protein GLI1 was identified in vincristine-resistant RMS and Ewings Sarcoma cell lines." (PMID 36826025, 2023). "mRNA expression of PPP1R1A, GLI1, FoxM1, and NR0B1 genes highly expressed in Ewing’s sarcoma cells was dependent on EWS-FLI1." (PMID 36194562, 2022). "To expand our investigations towards SMOi-resistant cancer cells, we turned to Ewing sarcoma (EWS) cells, where SMO-independent GLI1 expression is driven by the EWS–FLI1 fusion oncogene." (PMID 34439381, 2021). "The HH effector GLI1 is a direct transcriptional target of EWS-FLI1 and exerts key roles in Ewing sarcoma tumorigenesis." (PMID 31492956, 2019). "CDKN1C and a related member of the FOXO family, FOXO1, have previously been shown to inhibit Ewing Sarcoma growth, while FOXM1, GLI1 and PDGFRB have been shown to be growth-promoting in Ewing Sarcoma." (PMID 30237855, 2018). "Our work demonstrated that it reduces in a dose- and in a time-dependent manner the expression of Gli1, NR0B1, FOXM1 and VEGFA, some of the EWS-Fli1 target-genes considered as determining factors in the carcinogenesis of Ewing Sarcoma." (PMID 27006472, 2016). "GLI1 is a direct EWS-FLI1 target gene and a key regulator of the EWS-FLI1-dependent transcriptional network that drives tumorigenesis in Ewing sarcoma." (PMID 27259270, 2016). "In the specific case of Ewing sarcoma, ATO presented cytotoxicity in cell lines with upregulated GLI1 expression (TC-71, SKES and A4573), and curbed xenograft growth performed with TC-71 cells." (PMID 26258070, 2015). "In TC32 Ewing sarcoma cells, EWS/FLI1 knocking down using RNA interference produced a reduction in GLI1 expression levels." (PMID 26258070, 2015). "Because of our interest in the role of the GLI1 transcription factors in Ewing tumors, we became intrigued by a possible role for FOXM1 in Ewing tumor development." (PMID 23365673, 2013). "EWS-FLI1 knockdown based studies and transcriptional profiling data of various Ewing’s sarcoma cell lines have shown that gene like NR0B1, NKX2.2, EZH2, GLI1 are up regulated by EWS-FLI1." (PMID 23145994, 2012). "The strong and diffuse expression of membranous CD99 and positivity for NKX2.2 favors the diagnosis of Ewing sarcoma, which will typically be negative in GLI1-rearranged enteric tumors." (PMID 39851545, 2025).
Ewing sarcoma (continued). "Intriguingly, and in contrast to the usual observations in other cancer types, the dysregulation of GLI1 in Ewing sarcoma appears to be independent of Sonic Hedgehog (Shh) signaling." (PMID 37894854, 2023). "The clinical significance of GLI1 expression either through canonical Hedgehog signal transduction or through non-canonical mechanisms in rhabdomyosarcoma (RMS) or Ewing sarcoma (EWS) is incompletely understood." (PMID 32493277, 2020). "Therefore, we employed two Ewing sarcoma cell lines (TC71 and RDES) to examine GLI1 cytoplasmic/nuclear distribution in this cancer." (PMID 31492956, 2019). "Furthermore, activation of Gli1 (a Gli2 transcriptional target) seems to be a major downstream effector of the EWS-FLI1 oncoprotein which drives another SRBC tumor, Ewing Sarcoma." (PMID 22039523, 2011). "A secondary benefit of employing GLI1 inhibition in Ewing tumors is that GLI1, unlike EWS/FLI1, is felt to be involved in the pathogenesis of a large number of common malignancies." (PMID 19859563, 2009). "Additionally, these investigators employed RNA interference to establish that GLI1 expression in Ewing sarcoma cells (specifically TC71) relies on EWS/FLI1, and it was confirmed that GLI1 expression plays a crucial role in maintaining the transformed phenotype." (PMID 37894854, 2023). "GLI1 was found to be overexpressed in Ewing Sarcoma cell lines, regulated by EWS-FLI1 fusion protein independent of canonical Hh signaling pathway, as evidenced by lack of GLI1 response to exogenous SHH and cyclopamine treatment, and critical for Ewing Sarcoma proliferation." (PMID 36010600, 2022). "For instance, the Ewing Sarcoma/Friend Leukemia Integration 1 (EWS/FLI1) fusion oncogene, that characterizes Ewing Sarcoma Family Tumors (ESFT), has been shown to induce GLI1 transcription via direct binding to GLI1 promoter, with a consequent increase in the expression of activated GLI1 protein." (PMID 31244888, 2019).
rhabdomyosarcoma (31 papers, 2010 to 2025). A rare aggressive malignant mesenchymal neoplasm arising from skeletal muscle. "In GLI-hyperactivated rhabdomyosarcoma, SMARCA2 cooperates with GLI1 to enhance the chromatin accessibility of GLI-target genes, increasing their expression." (PMID 36556332, 2022). "In vivo studies showed that Gant61 treatment reduced both tumor growth and GLI1 expression in rhabdomyosarcoma." (PMID 33396427, 2020). "In this regard, a recent study has demonstrated the inhibition of human rhabdomyosarcoma xenografts by rapamycin through its effect on HH effector genes such as Gli1 and Gli 2 as well as PTCH1 and PATCH2." (PMID 30858923, 2019). "In this study, we identified and validated up to 29 novel targets of GLI1 genome‐wide in a rhabdomyosarcoma cell line." (PMID 30098229, 2018). "Rhabdomyosarcoma Rh36 cells were transfected with either siRNA targeting GLI1 or plasmids designed to over‐express GLI1 or RNA‐edited version of GLI1 (GLI1‐701G)." (PMID 30098229, 2018). "A closer examination of the murine rhabdomyosarcomas from the CAGGS-CreER; R26-SmoM2 mice suggested that they more closely resembled fetal rhabdomyoma histologically than aggressive rhabdomyosarcomas with upregulation of Gli1 and Ptch1 mRNA transcription, indicative of Hh pathway activation." (PMID 36010600, 2022). "The epithelial to mesenchymal transition was diminished by rapamycin in a xenograft model of rhabdomyosarcoma in a manner that inhibited both mTORC1 activity and Hh signaling, demonstrated by inhibition of growth and decreased expression of the Hh key genes: GLI1, GLI2, and PTCH, respectively." (PMID 33081032, 2020). "In addition, amplification of GLI1 has been also observed in rhabdomyosarcoma and GLI2 in oral squamous cell carcinoma." (PMID 30158435, 2018). "Gli1, a transcription factor that is activated following stimulation of the sonic hedgehog pathway, has been shown to activate the expression of plakoglobin in human rhabdomyosarcoma cells by binding to a Gli1 responsive element in the human plakoglobin gene (JUP) promoter." (PMID 28416759, 2017). "However, the incidence rates for GLI1 amplification vary significantly with the highest frequency (28%) reported in alveolar rhabdomyosarcomas." (PMID 21119888, 2010). "In the case of sarcomas, it has been shown that GLI1 and GLI2 can be overexpressed in various types of sarcomas, both in bone (osteosarcomas) and soft tissue (rhabdomyosarcomas)." (PMID 38275873, 2024). "Retrospective and human cell line studies of rhabdomyomas and rhabdomyosarcomas noted increased expression of PTCH1 and GLI1, suggesting activation of the Hh pathway." (PMID 36010600, 2022). "In mouse embryonic fibroblasts (MEFs), rhabdomyosarcoma and lung adenocarcinoma cells, MKL1 partnered with Jumonji domain-containing histone demethylase 1A (JMJD1A) to stabilize GLI1." (PMID 36010600, 2022). "Treatment of rhabdomyosarcoma and lung adenocarcinoma cells with the a JMJD-antagonist, JIB-04, inhibited tumor cell growth, decreased Hh-target gene expression, and induced GLI1 degradation." (PMID 36010600, 2022).
osteosarcoma (30 papers, 2010 to 2025). A usually aggressive malignant bone-forming mesenchymal neoplasm, predominantly affecting adolescents and young adults. "IHH, PTCH1 and GLI1 expression levels were strongly associated with each other and with tumour proliferation in human osteosarcoma cell lines and primary tumour specimens." (PMID 36457847, 2022). "In the current study, we determined the levels of expression of Hedgehog pathway components (IHH, SMO, PTCH1, and GLI1) in primary human osteosarcoma specimens and examined the association with clinical characteristics and patient outcome." (PMID 24799831, 2014). "Collectively, these findings suggested that the overexpression of GLI1 in OS tumor tissues and cisplatin-resistant cells may be functionally linked to osteosarcoma progression." (PMID 34659557, 2021). "Our current study clearly shows that the canonical pathway plays a critical role in Ptch1 deficiency-induced enchondroma and osteosarcoma formation, as inhibitors for Smo or Gli1/2, which are developed as candidate drugs to treat cartilage and bone tumors, suppressed tumorigenesis." (PMID 31482846, 2019). "Another group confirmed higher expression of Gli1 and Gli2 in canine osteosarcoma cell lines compared to normal canine osteoblasts." (PMID 37815662, 2023). "Gli1 and Gli2 showed expression predominantly in the nuclear compartment of osteosarcoma tumor cells." (PMID 32656074, 2020). "Our results demonstrated that Glaucocalyxin A induced apoptosis in osteosarcoma by inhibiting GLI1 via regulating PI3K/Akt signaling pathway in vitro and in vivo." (PMID 29899333, 2018). "In conclusion, our results suggested that Glaucocalyxin A induced apoptosis in osteosarcoma by inhibiting nuclear translocation of GLI1 via regulating PI3K/Akt signaling pathway." (PMID 29899333, 2018). "All our results above demonstrated that Glaucocalyxin A inhibited tumor growth by inducing apoptosis via inhibiting GLI1 nuclear translocation through regulating PI3K/Akt pathway in human osteosarcoma." (PMID 29899333, 2018). "The Gli-specific inhibitor GANT61 suppresses the levels of Gli1/2, Ptch1 and Pax6, cell growth and colony formation in osteosarcoma cells." (PMID 29899399, 2018). "Elucidation of the molecular mechanism showed that DGT suppresses osteosarcoma proliferation and metastasis by inhibiting the Hh/Gli1 pathway, mainly via GSK3 beta inactivation." (PMID 29899399, 2018). "Here we investigated the inhibitory effect of Glaucocalyxin A on the activation of GLI1 in human osteosarcoma cells." (PMID 29899333, 2018). "One possibility is that the GLI1 promoter is inactivated in human osteosarcomas by epigenetic modification." (PMID 20067614, 2010). "Lastly, LINC01123 enhances osteosarcoma proliferation and metastasis via the miR-516b-5p/Gli1 axis." (PMID 40255398, 2025). "The lack of significant transcriptional upregulation of common canonical Hh pathway target genes, including GLI1, in the moderately ciliated human osteosarcoma cell lines, all with a cilia frequency <20%, suggests that similar non-canonical Hh signaling mechanisms will be important to investigate." (PMID 37845394, 2023). "Abnormal activation of Gli1 in terminally-differentiated cells is a known oncogenic biomarker in multiple cancer subtypes such as leukaemia, basal cell carcinoma, medulloblastoma and osteosarcoma making it an ideal drug discovery target." (PMID 36457847, 2022). "Glaucocalyxin A was shown to increase apoptosis in human osteosarcoma cells, and this effect was accompanied by a concentration-dependent decrease in the nuclear concentration of GLI1, while the cytoplasmic concentration of GLI1 was increased." (PMID 33081032, 2020). "Moreover, Ptch1 deletion led to development of osteoarthritis-like phenotypes, exostoses, enchondroma, and osteosarcoma in Smo-Gli1/2-dependent manners." (PMID 31482846, 2019).
osteosarcoma (continued). "However, higher expression of the Hh ligand (Ihh) and its downstream target genes PTCH1 and Gli1 was observed in 43 clinical specimens of high-grade human osteosarcoma." (PMID 29899399, 2018). "In conclusion, as a natural compound from Chinese herb medicine, Glaucocalyxin A induced apoptosis and inhibited tumor growth by inhibiting nuclear translocation of GLI1 via regulating PI3K/Akt signaling pathway in osteosarcoma cells and in xenograft tumor model." (PMID 29899333, 2018). "Variable levels of IHH, SMO, PTCH1, and GLI1 expression were observed in the osteosarcoma samples." (PMID 24799831, 2014). "However, loss of Atg5 in a non-responsive, poorly ciliated 45Ca osteosarcoma cell line does not result in changes to cilia frequency or Gli1 mRNA." (PMID 37845394, 2023). "However, it could be shown that several Smoothened inhibitors are sufficient to inhibit Gli1 expression and proliferation in osteosarcoma cell lines." (PMID 32656074, 2020). "In osteosarcoma, LINC01123 promotes proliferation and metastasis via the miR-516b-5p/Gli1 axis, highlighting its oncogenic potential in bone cancer progression." (PMID 40255398, 2025). "Decreased expressions of Gli1, Gli2, Ptch1, and PAX6 were observed after treatment of canine osteosarcoma cells using GANT61." (PMID 37815662, 2023). "In bone malignancies such as osteosarcoma, the MAPK pathway promotes transcriptional activation of Gli1 and post-translational modifications of Gli1, leading to elevated Gli1 oncogenic activity." (PMID 36457847, 2022). "SJSA-1 was derived from an osteosarcoma of the femur with MDM2 proto-oncogene (MDM2) and GLI family zinc finger 1 (GLI1) gene amplification from a 19 year-old male patient." (PMID 29805751, 2018). "The results showed that knockdown of CNOT1 significantly inhibited the expression of GLI1, PTCH1, and PTCH2 in osteosarcoma cells." (PMID 28188704, 2017). "In this study of 43 high-grade human osteosarcoma samples, we detected high expression levels of the Hedgehog ligand gene, IHH, and target genes, PTCH1 and GLI1, in most samples." (PMID 24799831, 2014). "In this study of 43 osteosarcoma samples, we detected high expression levels of the Hedgehog ligand gene, IHH, and IHH target genes, PTCH1 and GLI1, in most osteosarcoma samples." (PMID 24799831, 2014). "Real-time PCR revealed that ATO prevented the transcription of GLI target genes, including PTCH1, GLI1, and GLI2, in human osteosarcoma cell lines." (PMID 23861973, 2013). "Real-time PCR showed that ATO decreased the expression of Hedgehog target genes, including PTCH1, GLI1, and GLI2, in human osteosarcoma cell lines." (PMID 23861973, 2013). "In the present study, we found that Shh, Dhh, PTCH1, SMO, GLI1 and GLI2 transcripts were over-expressed in osteosarcoma cell line." (PMID 20067614, 2010). "Six of these genes are increased (MYOM2, VEGFA, MUC1, IHH, GLI1 and GRIA1) and seven are decreased (VCAM1, EGFR, GPC3, IGF2, GNG12, GNGT1 and C3) in localized patients with poor prognosis that either relapse or die due to osteosarcoma." (PMID 38538763, 2024). "Besides IHH and GLI1, GPC3, which is downregulated in our poor prognosis osteosarcoma sub-group, has been shown to inhibit Hedgehog signaling in mouse development and in vitro in NIH 3T3 cells." (PMID 38538763, 2024). "On the other hand, GLI1 was down-regulated in human osteosarcoma biopsy specimens (data not shown)." (PMID 20067614, 2010). "Hedgehog signaling is of particular interest since GLI1 and IHH are both upregulated in the poor prognosis signature in patients with localized, non-metastatic osteosarcoma." (PMID 38538763, 2024). "Although GLI1 and GLI2 function as transcriptional activators of the Hh pathway, they have nonredundant roles in osteosarcoma." (PMID 25085524, 2014).
acute myeloid leukemia (26 papers, 2015 to 2025). Acute myeloid leukemia (AML) is a group of neoplasms arising from precursor cells committed to the myeloid cell-line differentiation. "Previously we demonstrated that overexpression of Hedgehog downstream mediators GLI1/2 confers an adverse prognosis to patients with acute myeloid leukemia (AML) and is correlated with a FLT3 mutated status." (PMID 28418873, 2017). "Concordant with the present findings, a previous study reported that over-expression of p-Akt is related to Gli1 protein over-expression in acute myeloid leukemia cells." (PMID 35834029, 2022). "Conversely, GLI1 reduces drug sensitivity via direct activation of the PI3K pathway in acute myeloid leukemia." (PMID 34899305, 2021). "It was known that GLI1 imparted drug resistance through inducible glucuronidation in the Acute Myeloid Leukemia." (PMID 28446712, 2017). "The expression of Shh, Gli1, and Smo was found to be significantly higher in high-risk MDS and acute myeloid leukemia associated with MDS patients in comparison with lower-risk MDS patients." (PMID 26317501, 2015). "Acute myeloid leukemia (AML) has been one of the most promising targets of HH inhibition therapy, either with Smo inhibitors or with further downstream inhibitors of GLI1 and GLI2 activators." (PMID 36091167, 2022). "Another proposed mechanisms is induction of the glucuronidation in acute myeloid leukemia (AML), where GLI1 is sufficient to drive UGT1A-dependent glucuronidation of ribavirin and cytarabine, leading to resistance." (PMID 30158435, 2018). "Recently, it has been shown that in acute myeloid leukemia (AML) patients, GLI1 expression induces resistance to ribavirin by modifying the activity of the drug." (PMID 26633513, 2015). "We could recently show that expression of HH pathway transcription factors GLI1 and GLI2 represents a negative prognostic marker for acute myeloid leukemia and that targeted inhibition of GLI1/2 mediates anti-leukemic effects in vitro and in vivo." (PMID 34333666, 2021).